ALDH1A3 (aldehyde dehydrogenase 1 family member A3)
Diseases named in the same sentence as ALDH1A3 in open-access papers (continued):
Sharing a sentence is not in itself a finding about the gene and the disease.
glioma (43 papers, 2015 to 2025). A benign or malignant brain and spinal cord tumor that arises from glial cells (astrocytes, oligodendrocytes, ependymal cells). "Herein, we present curcumin-based fluorescent probes that are able to bind to aldehyde dehydrogenase 1A3 (ALDH1A3), an enzyme overexpressed in glioma stem cells (GSCs) and associated with stemness and invasiveness of GBM." (PMID 36050388, 2022). "High expression of ALDH1A3 has been associated with the worse OS in various tumors, including glioma and pancreatic cancer." (PMID 35300699, 2022). "The fourth cluster included detrimental genes such as ALDH1A3 promoting stemness-like features in glioma, and is associated with worse survival." (PMID 32826850, 2020). "Mesenchymal marker in gliomas, where ALDH1A3 overexpression was significantly associated with tumor cell invasion." (PMID 28228731, 2017). "ALDH1A3 overexpression was significantly associated with high grade as well as the higher mortality of gliomas in survival analysis." (PMID 26575197, 2015). "However, the same source indicates that lower mRNA levels of ALDH1A1 and ALDH1A3 in high-grade gliomas are associated with an increased proportion of patients surviving more than 3 years." (PMID 39001459, 2024). "Similarly, in mesenchymal glioma stem cells, Aldefluor-positivity was associated with enriched ALDH1A3 expression and stemness." (PMID 36672441, 2023). "Isoforms ALDH1A1 and ALDH1A3 have particularly been implicated in GB although the exact roles of these isoforms in different types of glioma cells remain unclear." (PMID 35052687, 2021). "Another mechanism that is independent of RAR/RXR activation and may explain the importance of ALDH1A3 in gliomas and other tumors has been linked to an increased production of NADH that protects the cell from ferroptosis by the activation of ferroptosis suppressor protein 1 (FSP1)." (PMID 39001459, 2024). "A several number of evidence acknowledge that ALDH1A3 can be considered a characteristic hallmark of the Mes-GSCs, which may play an important role in glioma malignancy, given that it is involved in stem cell viability drug resistance and cells maintenance arguing tumor invasion." (PMID 36050388, 2022). "Importantly, we found that ALDH1A3 was highly expressed in Mes subtypes, and could be a novel diagnostic marker for Mes gliomas." (PMID 26575197, 2015). "Both local acetate production from acetaldehyde and NAD(P)H generation by ALDH1A3 activation also seem to play an important role in the growth and survival of gliomas and other cancers." (PMID 39001459, 2024). "In this study, ALDH1A3 was enriched in high-grade glioma and was determined to be essential for radioresistance in GBM cell lines." (PMID 36996494, 2023). "We have previously demonstrated that ALDH1A3 serves as a functional marker for mesenchymal glioma stem cells, which are characterized by radioresistance and activated glycolytic metabolism." (PMID 37551838, 2023). "We investigated the amount of ALDH1A3 present in glioma by analyzing mRNA microarray data from 325 glioma samples from the CGGA database." (PMID 36996494, 2023). "The mRNA expression level of ALDH1A3 in glioma tissue was significantly higher than in the adjacent normal tissue." (PMID 36996494, 2023). "qRT-PCR and Western blot further confirmed that the mRNA and protein expression of ALDH1A3 were increased in GBM cell line and glioma stem cell line expression of EGFRvIII (+), indicating that ALDH1A3 was the downstream target gene of EGFRvIII." (PMID 36980923, 2023). "ALDH1A3 protein expression affects various aspects of glioma cells, including apoptosis, proliferation, cell cycle, mitochondrial membrane potential, glucose consumption, lactate production and invasion ability." (PMID 36996494, 2023). "In this study, we found that the expression of ALDH1A3 was significant in glioma and crucial for radioresistance in GBM cell lines." (PMID 36996494, 2023).
glioma (continued). "In glioma, FOXD1 has been found to activate signaling pathways that contribute to the tumorigenicity of mesenchymal glioma stem cells by activating ALDH1A3 transcription." (PMID 37234983, 2023). "The high expression of ALDH1A3 is an important reason for the radiotherapy resistance of glioma stem cells; ALDH1A3 is highly expressed in MES GBM and can be used as a marker of MES GBM." (PMID 36980923, 2023). "It appeared that ALDH1A3 was expressed at higher levels in high-grade glioma than in low-grade glioma." (PMID 36996494, 2023). "In conclusion, our data first illustrated that aberrant expression of miR-320b enhanced cell proliferation and radioresistance via upregulated expression of ALDH1A3 in glioma." (PMID 36996494, 2023). "The expression profiles of CD133, CD44, Nestin, SOX2, Nanog, ALDH1A3 and OCT4, which are associated with glioma stem cell (GSC) signatures, were visualized in a heatmap." (PMID 36755314, 2023). "ALDH1A3 has also been found to promote the proliferation of glioma stem cells and to regulate the expression of the survival factor tissue transglutaminase in mesenchymal glioma stem cells." (PMID 36834608, 2023). "Bioinformatics analysis of the CGGA database revealed that glioma patients exhibiting high levels of ALDH1A3 expression had a poor clinical prognosis." (PMID 37551838, 2023). "Knockdown of ALDH1A3 inhibited the growth of the glioma Aldefluor-positive cells, suggesting that ALDH1A3 contributes to CSC-mediated tumorigenicity of mesenchymal glioma." (PMID 36672441, 2023). "To prove the role of the ALDH1a3 subtype as a glioma stem cell (GSC) marker, we performed sphere formation assays of ALDH1a3 wildtype and corresponding knockout glioma cell lines." (PMID 36552781, 2022). "Since autophagy is involved in both ferroptosis and ALDH1a3 regulation, we next investigated the role of autophagy in glioma cell response." (PMID 36552781, 2022). "Further development is warranted to characterize the role of ALDH1A3 and retinoic acid biosynthesis in glioma stem cell growth and differentiation." (PMID 34934174, 2021). "Here we show that depletion of ALDH1A3 resulted in a strong decrease in the production of RA in glioma-derived cells (U87MG) and MES GSCs." (PMID 34934174, 2021). "Here, we identified that ALDH1A3 as the main downstream target of ARL4C, and that ARL4C/ALDH1A3 axis was crucial for the tumorigenicity of glioma cells." (PMID 33403039, 2021). "For instance, ALDH1A3 has been reported to participate in extracellular matrix reorganization and cell adhesion in gliomas by inducing mesenchymal transformation and is responsible for the aggressiveness of mesenchymal-like glioma stem cells." (PMID 35116021, 2021). "Forkhead Box D1 (FOXD1) regulates the transcriptional activity of ALDH1A3 in glioma stem cells (GSCs) of MES subtype." (PMID 32680476, 2020). "In mesenchymal glioma CSCs, ALDH1A3 has been shown to regulate the expression of the survival factor tissue transglutaminase." (PMID 30733805, 2019). "ALDH1A3, an enzyme plays important role in alcohol metabolism and lipid peroxidation is a specific biomarker for glioma stem-like cells (GSCs), and cells with high expression of ALDH1A3 expression are shown to be highly tumorigenic." (PMID 30374421, 2018). "ALDH1A3 was shown to increase resistance towards γ-radiation and to be up-regulated in high grade gliomas, whereas ALDH1A3 promoter-methylation correlated with longer survival time." (PMID 29854309, 2018). "Several upstream and downstream mediators of the malignant properties of ALDH1A3 in glioma cells have been identified." (PMID 30538217, 2018). "The purpose of our study was to elucidate the mechanisms by which ALDH1A3 regulated in glioma and to provide practical tools for clinical application." (PMID 30538217, 2018). "ALDH1A3 was shown to support clonogenicity and tumorigenicity of glioma stem cells by enhancing the glycolytic pathway." (PMID 27845622, 2016).
glioma (continued). "Elevated ALDH1A3 expression in mesenchymal glioma stem cells highlights the potential of this isozyme as a prognosis marker and drug target." (PMID 27759097, 2016). "In the current study, we found that the mRNA expression level of ALDH1A3 in gliomas was correlated to many Mes subtype markers and tumor invasion associated genes." (PMID 26575197, 2015). "For example, enriched expression for ALDH1A3 was shown to confer specific metabolic features to glioma “stem-like” cells." (PMID 25868979, 2015). "By whole-genome transcriptome microarray and mRNA sequencing analysis, we compared the expression of ALDH1A3 in high- and low- grade gliomas as well as different molecular subtypes." (PMID 26575197, 2015). "In this study, by whole-genome transcriptome microarray and mRNA sequencing analysis, we compared the mRNA expression level of ALDH1A3 in high- and low- grade gliomas and different molecular subtypes." (PMID 26575197, 2015). "In conclusion, ALDH1A3 can serve as a novel marker of Mes phenotype in gliomas with potential clinical prognostic value." (PMID 26575197, 2015). "Meanwhile, the mRNA expression level of ALDH1A1 and ALDH1A3 in high and low grade gliomas were compared by TCGA whole transcriptome sequencing data." (PMID 26575197, 2015). "In the present study, we analyzed the ALDH1A3 mRNA expression in different grade gliomas demonstrated a significant increase from low- to high- grade gliomas." (PMID 26575197, 2015). "In human GBM and other gliomas, ALDH1A3 is involved in different biochemical pathways that may explain the importance of the enzyme for tumor proliferation and survival." (PMID 39001459, 2024). "Similarly, in mesenchymal glioma stem cells, transcription factor foxhead box D1 (FOXD1) regulates ALDH1A3 its expression, and the FOXD1-ALDH1A3 axis is critical in the self-renewal and tumorigenicity properties of glioma stem cells." (PMID 36672441, 2023). "In contrast, the results of another study suggested that ALDH1A3 might be the dominant subtype that determines ALDEFLUOR activity in glioma." (PMID 36651035, 2023). "Moreover, glioma patients with a high expression level of ALDH1A3 had a shorter lifespan than those with a lower amount of ALDH1A3." (PMID 36996494, 2023). "Moreover, it shows increased expression of FOXD1 in mesenchymal glioma stem cells and contributes to glial neoplasms by upregulating the expression of the aldehyde dehydrogenase isoform ALDH1A3 via directly activating its promoter." (PMID 37906341, 2023). "Furthermore, our previous study has identified ALDH1A3 as a functional biomarker for mesenchymal glioma stem cells that are resistant to radiation." (PMID 36996494, 2023). "Additionally, Pearson correlation analysis revealed that the expression of circCABIN1 was positively correlated with the expression of ALDH1A3 in 180 glioma patient tissues." (PMID 36755314, 2023). "Nevertheless, the role that miRNAs play in the ALDH1A3 signaling pathways in regulating the radioresistance of glioma remains unclear." (PMID 36996494, 2023). "Of the many ALDH isoforms, we and others have implicated the elevated expression of ALDH1A3 in mesenchymal glioma stem cells (MES GSCs) as a target for the development of novel therapeutics." (PMID 34934174, 2021). "ALDH1A3-FL was found to prevail over truncated variants in non-stem glioma cells but not in GSCs, showing a clear predominance of truncated variants over the full-length protein." (PMID 35052687, 2021). "However, gliomas with low expression of ALDH1A3 were more likely to be the PN subtype, and suppression of ALDH1A3 inhibited PN GSCs’ proliferation." (PMID 32429463, 2020). "Inhibition of ALDH1A3 selectively suppresses the growth of mesenchymal glioma CSCs." (PMID 30733805, 2019).
glioma (continued). "Two distinct tumour-derived GSC subtypes were identified in high-grade glioma: the proneuronal glioma stem cells (PN GSCs) and the mesenchymal glioma stem cells (Mes GSCs) with elevated expression of human ALDH1A3 being observed in Mes GSCs with respect to PN GSCs23." (PMID 27759097, 2016). "Indeed, ALDH1A3 was shown to support self-renewal and clonogenic potential of cancer stem cells, including glioma stem cells, which can differentiate into neurons and glial cells like NPCs." (PMID 27845622, 2016). "ALDH1A3 promotes self-renewal and clonogenic potential of glioma stem cells, suggesting that its reduced expression may account for the phenotype of Khdrbs1-/- NPCs." (PMID 27845622, 2016). "In view of high expression in Mes gliomas and its function in cell invasion, ALDH1A3 may serve as a potential therapeutic target for Mes subtype gliomas." (PMID 26575197, 2015). "ALDH1A3 was characteristically highly expressed in Mesenchymal (Mes) subtype gliomas." (PMID 26575197, 2015). "Here, we investigate the clinical significance and potential function of ALDH1A3 in gliomas." (PMID 26575197, 2015). "In addition to be a novel marker of GSCs, ALDH1A3 is likely to play an important role in glioma, especially in a subtype dependent manner." (PMID 26575197, 2015). "In our study, we assessed whether the invasiveness of glioma cells could be inhibited by ALDH1A3 silencing in vitro." (PMID 26575197, 2015). "The preferential mRNA expression of ALDH1A3 in Mes subtype of gliomas is noteworthy." (PMID 26575197, 2015). "Additionally, referring to its up-regulation in high-grade and Mes subtype gliomas, ALDH1A3 was supposed to be closely related to glioma cell invasion." (PMID 26575197, 2015). "However, the upstream miRNA that plays in the ALDH1A3 signaling pathways in regulating the radioresistance of glioma remains unclear." (PMID 36996494, 2023). "Furthermore, ALDH1A3 could reportedly affect glioma glucose metabolism and is recognized as a stem-like cells biomarker." (PMID 35116021, 2021). "Thus, we proposed that ALDH1A3 can serve as a novel biomarker of Mes subtype gliomas." (PMID 26575197, 2015). "In conclusion, ALDH1A3 might be a novel prognostic marker in gliomas." (PMID 26575197, 2015). "In addition to the fact that ALDH serving as a functional cancer stem cell marker in many human tumors, we speculate that gliomas with different ALDH1A3 mRNA expression level might have cells from different origins." (PMID 26575197, 2015). "ALDH1A3 could also be a novel marker for Mes subtype gliomas." (PMID 26575197, 2015). "Moreover, the reduction of cell invasive ability in ALDH1A3 knockdown cell lines indicated that strategies designed to target ALDH1A3 might lead to more effective therapies for Mes subtype gliomas." (PMID 26575197, 2015). "Finally, functional experiments in vitro revealed that ALDH1A3 could not only be a novel biomarker of Mes phenotype in gliomas, but was correlated with tumor cell invasion." (PMID 26575197, 2015). "In TCGA glioma samples, USP14 showed positive correlation with CD44 and ALDH1A3, and inverse correlation with PN markers, SOX2 and OLIG2." (PMID 39990235, 2025). "ELF4 is elevated in high grade gliomas, particularly in glioma and neuronal stem cell markers, including CD44, CD36, CD15, CD70, S100A4, and ALDH1A3." (PMID 38539424, 2024). "Recent research demonstrated that KIF4A knock-down can suppress the glioma stem cells marker expression including CD133, ALDH1A1, and ALDH1A3, meanwhile, KIF4A over-expression can promote the epithelial-to-mesenchymal transition (EMT) of glioma." (PMID 38937742, 2024). "To explore the potential regulatory mechanism of ALDH1A3 in glioma, we performed bioinformatics analysis of target miRNAs using the ENCOR1, miRWalk, and TargetScan databases to examine the consensus binding sites of ALDH1A3." (PMID 36996494, 2023). "However, the molecular mechanism of ALDH1A3 involved in radioresistance in glioma remains unclear." (PMID 36996494, 2023).
glioma (continued). "We treated U87 cells, a glioma cell line, with sphere-forming media and observed that the expression of CSC marker proteins, including CD133, ALDH1A1, and ALDH1A3, was diminished in the group where KIF4A expression was knocked down." (PMID 38067227, 2023). "ALDH1A3 levels are also dysregulated at the protein level in glioma stem cells, where ubiquitin-specific protease 9X (USP9X) deubiquitinates ALDH1A3, leading to its increased stabilization and levels." (PMID 36672441, 2023). "Glioma stem cells (GSCs) characterized by ALDH1a3 expression seem to be the most resistant cell type in GBM, and ALDH1a3 enzymatic activity seems to be involved in the development of the resistant phenotype." (PMID 36552781, 2022). "ALDH1A3 is the most upregulated between ALDH high and low subgroups of glioma cells among 19 isoform of ALDH family." (PMID 32680476, 2020). "Collectively, these data suggest that ALDH1A3 can serve as a prognostic biomarker of gliomas, and as one of the leading targets for more effective therapies for MES-subtype gliomas." (PMID 32429463, 2020). "In a baseline activity screen of in vitro glioma models, we identified that GBM cell lines with high ALDH enzyme activity positively correlate with ALDH1A3 protein overexpression." (PMID 30538217, 2018). "In previous studies, ALDH1A3 and ALDH1A1 were supposed to be two important ALDH isoforms in gliomas." (PMID 26575197, 2015). "By whole-genome expression profiling data, we compared the mRNA expression level of ALDH1A3 and ALDH1A1 in low-grade gliomas (LGG, n = 122) and high-grade gliomas (HGG, n = 179)." (PMID 26575197, 2015). "Analysis of the TCGA dataset showed that ALDH16A1, ALDH3B1, ALDH1A3, ALDH3A1, ALDH7A1 were significantly increased in IDH wildtype gliomas, while ALDH2, ALDH6A1, ALDH5A1, ALDH1A1, ALDH1L2, ALDH18A1, ALDH1B1 expression were higher in IDH mutant gliomas than IDH wildtype gliomas." (PMID 35116021, 2021). "Our investigations reveal for the first time the abundance of short ALDH1A3 peptides that appear prevailing over the full-length form in GSCs but not in non-stem glioma cells." (PMID 35052687, 2021). "In glioma, FOXD1 upregulates ALDH1A3 to promote stemness properties." (PMID 31795213, 2019). "Therefore, co-expression of ALDH1A3 and a well-known MES differentiation marker CD44 in glioma cells reveals its potential as a MES marker." (PMID 30538217, 2018). "By shRNA, ALDH1A3 was transiently knockdown in U87 and LN229 glioma cells." (PMID 26575197, 2015). "The STAT3 pathway may modulate the number of NSCLC- and mesothelioma- ALDHbright cells and, notably, glioma cells of the mesenchymal subtype, which require STAT3 (and CEBPβ) for their survival, exhibited high levels of ALDH1A3 expression." (PMID 25868979, 2015). "Some preliminary studies have found that ALDH1A3 may play an important role in glioma malignant progression, but so far there was no conclusive conclusion." (PMID 30538217, 2018). "But the biological functions of ALDH1A3 in gliomas were not well elucidated yet." (PMID 26575197, 2015). "However, MCI-INI-3 displays cytotoxic effects at 15 μM on non-ALDH1A3-expressing glioma stem cell lines, indicating that it may not have an ALDH1A3-specific impact on glioma stem cell viability." (PMID 38612911, 2024). "Although the expression of ALDH1A3 is not restricted solely to GSCs, the composite ALDH1A3+/ALDH1A1-phenotype is a characteristic trait of GSCs whereas the concomitant expression of both ALDH1A3 and ALDH1A1 isoforms appears to be associated with glioma cells lacking stemness." (PMID 35052687, 2021). "Notably, although ALDH1A3∆30, ALDH1A3∆17 and ALDH1A3∆12 could also be detected in non-stem glioma lines LN229 and U87, their proportions relatively to ALDH1A3-FL differed between GSCs and non-stem glioma cells." (PMID 35052687, 2021).